ARHGAP30 (Rho GTPase activating protein 30)
Description:
GTPase-activating protein (GAP) for RAC1 and RHOA, but not for CDC42.
Synonyms: FLJ00267
Tractability: PROTAC: ubiquitination databases record sites on it; its protein half-life has been measured.
Gene: Protein-coding gene on chromosome 1 (161,046,946 to 161,069,970, reverse strand). Ensembl gene ENSG00000186517.
Subcellular location: Cytoplasmic vesicle
Subcellular location (Human Protein Atlas): Vesicles
Pathways (Reactome):
Signal Transduction: CDC42 GTPase cycle; RAC1 GTPase cycle; RHOA GTPase cycle; RHOU GTPase cycle
Gene Ontology:
Molecular function: GTPase activator activity; protein binding
Biological process: negative regulation of Rho protein signal transduction; regulation of small GTPase mediated signal transduction; small GTPase-mediated signal transduction; signal transduction
Cellular component: cytosol; cytoplasmic vesicle
Genetic constraint (gnomAD): Loss-of-function variants: 23 observed, 75.91 expected, observed/expected ratio (o/e) 0.3, 90% interval 0.22 to 0.43. The upper end of that interval is the gene's LOEUF score, 0.43, which puts it in group 1 of 6, group 1 being the genes least tolerant of losing a copy. Missense variants: 1,301 observed, 1,434.9 expected, observed/expected ratio (o/e) 0.91, 90% interval 0.87 to 0.95. Synonymous variants: 570 observed, 548.88 expected, observed/expected ratio (o/e) 1.04, 90% interval 0.97 to 1.11.
Homologues: Orthologues: chimpanzee ARHGAP30 (99% identical), macaque ARHGAP30 (96% identical), pig ARHGAP30 (83% identical), dog ARHGAP30 (82% identical), guinea pig ARHGAP30 (80% identical), rat Arhgap30 (77% identical), rabbit ARHGAP30 (76% identical), mouse Arhgap30 (76% identical), tropical clawed frog arhgap30 (39% identical), Drosophila melanogaster CdGAPr (21% identical), Caenorhabditis elegans rrc-1 (10% identical). Paralogues in human: ARHGAP32 (30% identical), ARHGAP31 (25% identical), ARHGAP33 (24% identical).
Diseases named in the same sentence as ARHGAP30 in open-access papers:
ARHGAP30 is named in the same sentence as 14 diseases in open-access papers, as found by Europe PMC text mining. Sharing a sentence is not in itself a finding about the gene and the disease. The quoted sentences say what the papers report.
colorectal cancer (9 papers, 2015 to 2024). A primary or metastatic malignant neoplasm that affects the colon or rectum. "For example, low ARHGAP30 expression promoted the proliferation and migration of colorectal carcinoma cells." (PMID 36168627, 2022). "For instance, ARHGAP30 was downregulated in lung cancer and colorectal cancer but overexpressed in pancreatic cancer." (PMID 33579308, 2021). "However, a recent report showed that ARHGAP30 is required for acetylation and functional activation in colorectal cancer." (PMID 25977731, 2015).
lung carcinoma (8 papers, 2020 to 2024). "Moreover, a low ARHGAP30 level is associated with the activation of Wnt/β-catenin signaling pathways and further leads to lung cancer cell proliferation, migration, and invasion." (PMID 34917619, 2021). "The ARHGAP30 (Rho GTPase activating protein 30) gene encodes a Rho GTPase-activating protein, with a role in regulating cell adhesion, as well as suppressing lung cancer cell proliferation, migration and invasion." (PMID 32245826, 2020). "The red line in the figure shows that the expression level of ARHGAP30 in lung cancer tissue was significantly lower than that in normal tissue." (PMID 34910688, 2021). "ARHGAP30 suppresses lung cancer by inhibiting Wnt/-catenin signaling." (PMID 36276869, 2022). "This intricate molecular interplay between KIAA1429, ARHGAP30, and the PI3K/AKT signaling pathway offers significant insights into the mechanistic pathways driving LUAD progression, highlighting potential targets for therapeutic intervention in this form of lung cancer." (PMID 38717936, 2024).
pancreatic cancer (4 papers, 2019 to 2025). "In some studies on the relationship between ARHGAP30 and cancer, upregulation of ARHGAP30 attenuated pancreatic cancer progression by inactivating the β-catenin pathway." (PMID 34910688, 2021).
lung adenocarcinoma (3 papers, 2020 to 2024). A carcinoma that arises from the lung and is characterized by the presence of malignant glandular epithelial cells. "The study of ARHGAP30-associated immune infiltration will provide a new direction for immunotherapy of lung adenocarcinoma." (PMID 34910688, 2021). "Gene set enrichment analysis revealed that many pathways associated with ARHGAP30 should be studied to improve the diagnosis, treatment, and prognosis of lung adenocarcinoma." (PMID 34910688, 2021). "The association of ARHGAP30 expression with tumor-infiltrating lymphocytes, immunostimulators, major histocompatibility complex molecules, chemokines, and chemokine receptors in lung adenocarcinoma tissues was also analyzed." (PMID 34910688, 2021). "High expression of KIAA1429 in lung adenocarcinoma increases the m6A level of the downstream target gene ARHGAP30, which leads to a decrease in the expression of ARHGAP30, thus contributing to lung adenocarcinoma progression." (PMID 38717936, 2024). "The location of ARHGAP30 methylation in the lung adenocarcinoma cases was on chromosome 1, 161015000 to 161,069905." (PMID 34910688, 2021). "Gene ontology biological process based gene set enrichment analysis of ARHGAP30 in lung adenocarcinoma." (PMID 34910688, 2021). "Gene ontology cellular component based gene set enrichment analysis of ARHGAP30 in lung adenocarcinoma." (PMID 34910688, 2021). "Gene ontology molecular function-based gene set enrichment analysis of ARHGAP30 in lung adenocarcinoma." (PMID 34910688, 2021). "ARHGAP30 expression in lung adenocarcinoma correlated positively, whereas methylation of ARHGAP30 correlated negatively, with levels of tumor infiltrating lymphocytes." (PMID 34910688, 2021). "KEGG pathway based gene set enrichment analysis of ARHGAP30 in lung adenocarcinoma." (PMID 34910688, 2021). "Patients with lung adenocarcinoma with high DNA methylation of ARHGAP30 had poor prognosis." (PMID 34910688, 2021). "Therefore, the present study aimed to assess the differences in expression of ARHGAP30 between lung adenocarcinoma tissues and normal tissues and the relationship between DNA methylation and ARHGAP30 expression in lung adenocarcinoma." (PMID 34910688, 2021). "Wikipathway gene set enrichment analysis of ARHGAP30 in lung adenocarcinoma." (PMID 34910688, 2021). "The prognosis of patients with lung adenocarcinoma with low ARHGAP30 expression was also poor." (PMID 34910688, 2021). "PPI BIOGRID network gene set enrichment analysis of ARHGAP30 in lung adenocarcinoma." (PMID 34910688, 2021). "Transcription factor network gene set enrichment analysis of ARHGAP30 in lung adenocarcinoma." (PMID 34910688, 2021). "We speculated that DNA methylation of ARHGAP30 suppresses ARHGAP30 expression, which reduces tumor immunity, leading to poor prognosis for patients with lung adenocarcinoma." (PMID 34910688, 2021). "The relationship between ARHGAP30 expression and lung adenocarcinoma is unclear." (PMID 34910688, 2021). "Kinase target network gene set enrichment analysis of ARHGAP30 in lung adenocarcinoma." (PMID 34910688, 2021). "Panther pathway gene set enrichment analysis of ARHGAP30 in lung adenocarcinoma." (PMID 34910688, 2021). "Reactome pathway gene set enrichment analysis of ARHGAP30 in lung adenocarcinoma." (PMID 34910688, 2021).
glioma (2 papers, 2023 to 2024). A benign or malignant brain and spinal cord tumor that arises from glial cells (astrocytes, oligodendrocytes, ependymal cells). "Emphasizing the role of ARHGAP30, integral to our model, its impact on glioma severity and the credibility of our risk assessment model were substantiated through RT‐qPCR, Western blot analysis, and cellular functional assays." (PMID 39075640, 2024). "These experiments consistently demonstrated that ARHGAP30 significantly enhanced the proliferation of glioma cells, thereby corroborating the association between high ARHGAP30 expression and unfavourable glioma prognosis." (PMID 39075640, 2024). "Notably, in our model, the elevated expression of the ARHGAP30 gene in gliomas was linked to increased cellular invasiveness, as evidenced by cellular functional assays." (PMID 39075640, 2024). "In the 6‐gene model developed for glioma prognosis, ARHGAP30 stood out due to its lower p‐value in univariate Cox analysis and its pronounced correlation with CD8+ T cells." (PMID 39075640, 2024). "To substantiate the link between ARHGAP30 upregulation and adverse outcomes in glioma, we conducted a series of cellular assays." (PMID 39075640, 2024). "Our findings may provide good evidence to explain ARHGAP30 in gliomas in EMT targeting and immunotherapy." (PMID 39075640, 2024). "Overexpression of PRDM13 in U87 glioma cells significantly inhibits cell migration and invasion by interacting with deleted liver cancer 1 (DLC1) and ARHGAP30 (Rho GTPase-activating protein 30) genes." (PMID 36982660, 2023). "However, there are no relevant basic studies on ARHGAP30 in glioma, and we found that by overexpressing ARHGAP30 in GBM cell lines, ARHGAP30 significantly promoted the proliferation of glioma cells." (PMID 39075640, 2024).
osteoarthritis (2 papers, 2021 to 2023). A noninflammatory degenerative joint disease occurring chiefly in older persons, characterized by degeneration of the articular cartilage, hypertrophy of bone at the margins and changes in the synovial membrane. "Its putative role and increased expression in high-grade osteoarthritis cartilage, suggests involvement of ARHGAP30 in cartilage repair mechanisms during osteoarthritis pathogenesis." (PMID 33473114, 2021).
pancreatic ductal adenocarcinoma (2 papers, 2018 to 2020). An infiltrating adenocarcinoma that arises from the epithelial cells of the pancreas. "Besides, ARHGAP30 was found had significantly improved OS of pancreatic ductal adenocarcinoma." (PMID 30587197, 2018).
atherosclerosis (1 paper, 2024). A disease characterized by the build-up of fatty material and calcium deposition in the arterial wall resulting in partial or complete occlusion of the arterial lumen. "Firstly, heatmap analysis of the three differential genes including MYBL1, ARHGAP30 and FAM20A were performed and found that MYBL1 had the highest expression in early atherosclerotic tissues and the lowest expression in advanced atherosclerosis, while FAM20A and ARHGAP30 had the opposite trend." (PMID 38797732, 2024).
cervical cancer (1 paper, 2024). A primary or metastatic malignant neoplasm involving the cervix. "In cervical cancer, ARHGAP30 may reduce ribosome biosynthesis and protein synthesis by promoting ubiquitination of NCL and thus tumour cell growth." (PMID 39075640, 2024).
tumor (5 papers, 2020 to 2024). "The association of ARHGAP30 expression with tumor-infiltrating lymphocytes (TILs), immunostimulators, major histocompatibility complex (MHC) molecules, chemokines, and chemokine receptors in LUAD tissues were also analyzed." (PMID 34910688, 2021). "Suppressing KIAA1429 results in reduced m6A levels in the mRNA of the target gene ARHGAP30, boosting its stability and expression, thus inhibiting tumor proliferation and metastasis." (PMID 38717936, 2024). "Considering earlier research showing ARHGAP30's tumor‐inhibiting function in LUAD by hindering LUAD cell growth, we aimed to explore whether KIAA1429 influences the PI3K/AKT signaling pathway via its regulatory effect on ARHGAP30, thereby impacting LUAD proliferation and metastasis." (PMID 38717936, 2024). "However, whether there is a difference in the expression of ARHGAP30 in LUAD, a relationship between the expression of ARHGAP30 in LUAD and DNA methylation, and whether these affect patient’s prognosis, survival, and tumor immune infiltration, are unclear and require further study." (PMID 34910688, 2021). "Within LUAD tissues, ARHGAP30, a tumor suppressor, shows a substantial decrease and a negative correlation with KIAA1429 expression, suggesting KIAA1429‐triggered m6A alterations directly affect ARHGAP30." (PMID 38717936, 2024).
cancer (3 papers, 2019 to 2024). A tumor composed of atypical neoplastic, often pleomorphic cells that invade other tissues. "Our analysis shows that ARHGAP30 exhibits notable differential skew between cancer and control cohorts." (PMID 31861976, 2019).
ARHGAP30 also shares sentences with these, for which no sentence is quoted: infection (1 paper); osteosarcoma (1); viral myocarditis (1).